MMP9 (matrix metallopeptidase 9)
Diseases named in the same sentence as MMP9 in open-access papers (continued):
Sharing a sentence is not in itself a finding about the gene and the disease.
endothelial dysfunction (continued). "The expression of endothelial dysfunction markers VCAM1, MMP9, and NOX1 in the lactate-treated group was significantly elevated, as indicated by the RT-qPCR." (PMID 41213933, 2025). "Preclinical studies suggest that HHC mitigates vascular remodeling and endothelial dysfunction by reducing the expression of transforming growth factor β (TGF-β1) and matrix metalloproteinase-9 (MMP-9)." (PMID 40283989, 2025). "As the main finding, this study showed that in patients with T2DM Taurine exposure for 8 weeks significantly decreased the biomarkers related to endothelial dysfunction including VCAM, ICAM-1, and MMP-9." (PMID 35870947, 2022). "GAG binding and activation of enzymes like MMP9, HPSE, hyaluronidase, and neuraminidases are common requirements for both NS1- and S-mediated endothelial dysfunction." (PMID 36494335, 2022). "Our results also show that individuals with HbSC who presented TGF-β1 levels above the median value also exhibited higher levels of MMP-9, which reinforces the role of TGF-β in angiogenesis, vasculopathy, and endothelial dysfunction." (PMID 33790690, 2021). "Curcumin was found to improve endothelial dysfunction by increasing NO bioavailability and decreasing levels of the angiotensin-converting enzymes MMP-2 and MMP-9 in hypertensive rats." (PMID 34444956, 2021). "In serum samples, we assessed inflammatory markers (IL-1β, TNF-RI, TNF-RII, sFas, sFasL, MMP-9, TIMP-1, and TGF-β1), endothelial dysfunction markers (sE-selectin, sICAM-1, and sVCAM-1), and volume-related marker (NT-proBNP)." (PMID 27034745, 2016). "MMP-2 and MMP-9 were upregulated in diabetic CKD arteries and correlated with stiffening and endothelial dysfunction." (PMID 27042350, 2016). "In our cohort of obese children and adolescents, several biomarkers of vascular injury and endothelial dysfunction, including PAI-1, sICAM-1, MMP-9, MPO and VEGF, were significantly and positively correlated with circulating endotoxin concentrations." (PMID 26819711, 2015). "Gene expression of MMP-2 and MMP-9 in peripheral blood leukocytes and circulating levels of MMP-2, MMP-9, pro-inflammatory cytokines (TNF-α, IL-6), and endothelial dysfunction markers (Endothelin-1 [ET-1], adhesion molecules) were quantified via qRT-PCR and ELISA." (PMID 41598609, 2026). "Consistent with this axis, human cohort data in untreated familial hypercholesterolemia demonstrate network correlations among PON1 arylesterase activity, MMP-9, and inflammatory mediators (sCD40L, S1P), positioning PON1 within an HDL-inflammation-protease module relevant to endothelial dysfunction." (PMID 41304763, 2025). "This study examines how glypican-1 shedding, matrix metallopeptidase 9 (MMP9), and the pro-inflammatory cytokine IL-1β may contribute to endothelial dysfunction in patients undergoing on-pump surgery with an extended CPB." (PMID 39857617, 2024). "In addition, matrix metalloproteinase-9 (MMP-9) in NETs can stimulate MMP-2 in ECs, resulting in endothelial dysfunction." (PMID 36059483, 2022). "Finally, other biomarkers of endothelial dysfunction are increased in women with PCOS, such as visfatin, VEGF, matrix metallopeptidase 9 (MMP9), high-mobility group box 1, pentraxin 3, and soluble lectin-like oxidized low-density lipoprotein receptor-1." (PMID 33806677, 2021). "In addition, neutrophil intracellular MMP-9 is externalized during NET formation, and MMP-9 induces endothelial dysfunction by activating MMP-2, which participates in the SLE disease process." (PMID 32774152, 2020). "Elevated concentrations of MMP-9 have been reported in women with PCOS that are related to the occurrence of angiogenesis and endothelial dysfunction seen in PCOS, as well as normal functions such as follicular growth, ovulation, and establishment of the luteal corpus." (PMID 33419373, 2020).
endothelial dysfunction (continued). "Similar to that study, here we analyzed MMP-9–TIMP-1 immunocomplexes in plasma samples from hypertensive patients with or without albuminuria as an indicator of endothelial dysfunction and arterial stiffness." (PMID 28791014, 2017). "We did indeed observe regulation of several factors denoting endothelial dysfunction (CD31, VCAM, thrombospondin) and tissue remodeling (MMP9, chitinase 3‐like 1) in IMRT, but not in SABR patients." (PMID 32519025, 2020). "Interestingly, it was demonstrated that in atherosclerotic plaque, MMP-2 levels decreased, compared to nonatherosclerotic human tissues, whereas MMP-9 levels increased, showing that MMP-9 activity contributes to endothelial dysfunction." (PMID 32454796, 2020).
lung diseases (69 papers, 2007 to 2025). "Increased MMP9 in respiratory samples has been linked with several lung diseases, including paediatric patients with acute respiratory distress syndrome (ARDS)." (PMID 37474963, 2023). "Further, we compared the effect of Mmp9 vs. NE deficiency on lung function to assess their relative contributions to CF-like lung disease in βENaC-Tg mice." (PMID 36362203, 2022). "Elevated levels of NFkB and metalloproteinases (MMP), namely MMP-2 and MMP-9, are associated with increased NE activity and CF lung disease pathogenesis and progression." (PMID 33546140, 2021). "Elevated levels of NFκB and metalloproteinases (MMP) (i.e., MMP-2 and MMP-9) are also known to be associated with increased NE activity and CF lung disease." (PMID 33546140, 2021). "IGFBP-1 and MMP-9 were selected to be associated with H3.1 containing cf-nucleosomes because of their correlation with lung disease." (PMID 32807242, 2020). "Gelatinases MMP2 and MMP9 are capable of cleaving type IV collagen present in the basement membrane and have been implicated in a variety of pulmonary diseases." (PMID 22496659, 2012). "A high MMP9/TIMP1 ratio has been shown to be associated with a less severe progression of different lung diseases." (PMID 21547259, 2011). "An increase in the MMP-9/TIMP-1 ratio was also associated with the severity of lung disease and could indicate airway inflammation and bronchial injury while causing clinical differences in chronic airway diseases." (PMID 37509076, 2023). "Furthermore, studies using MMP-9 deficient mice demonstrated the role of MMP-9 in lung diseases caused by IAV infection." (PMID 36142454, 2022). "Moreover, MMP9, which has been implicated in the pathogenesis of several lung diseases and injury, has been shown to increase the expression of IL-6 in response to O3." (PMID 33260937, 2020). "Gelatinases (MMP2 & MMP9) have been implicated in the pathogenesis of various lung diseases." (PMID 31842927, 2019). "For example, previous studies showing that increased levels of Matrix metallopeptidase (MMP-9) is associated with more severe lung disease in CF prompted the development of doxycycline, an antibiotic that is also a potent inhibitor for MMP-9, as a CF therapeutic." (PMID 30813620, 2019). "Imbalanced ratios of MMP-9 to its specific tissue inhibitors have been implicated in the pathogenesis of various lung diseases, including chronic lung injury in preterm infants, promotion of airway remodeling, disease exacerbation and the perturbance of alveolar development." (PMID 29558521, 2018). "Interestingly, patients with many of the lung diseases in which MMP-9 levels are elevated are also more susceptible to pulmonary infections, such as in COPD and CF." (PMID 22860023, 2012). "Clinical studies have suggested that, among the various biomarkers potentially associated with lung disease, MMP-9 may be particularly important, although there have been few longitudinal studies of MMP-9 and few pulmonary status outcomes examined." (PMID 21429222, 2011). "The activity of MMP-2 and MMP-9 has been widely studied in animals and humans, presenting itself as a promising diagnostic biomarker and therapeutic target in various pathologies, such as changes in the vascular system, ischemic lesions, neurodegenerative diseases, lung diseases, and cancer." (PMID 38612961, 2024). "In addition, neutrophils, one type of granulocytes, secrete serine proteases including neutrophil elastase, cathepsin G and proteinase-3, as well as MMP-8 and MMP-9, which may lead to destruction of the alveolar tissue and increase the risk of lung disease." (PMID 30400967, 2018). "Serum MMP-9 concentrations may be raised and associated with pulmonary disease severity." (PMID 19789647, 2009). "While the evaluation of the in vivo effects of genetic deletion of Mmp9 provides important insights into the role of this protease in the complex in vivo pathogenesis of CF-like lung disease, our study also has limitations." (PMID 36362203, 2022).
lung diseases (continued). "Matrix metalloproteinase-9 (MMP-9) is a zinc-dependent enzyme with collagenase activity, and it is importantly involved in the establishment of various lung diseases." (PMID 35883784, 2022). "MMP-9 is a zinc-dependent enzyme with collagenase activity importantly involved in the establishment of various lung diseases." (PMID 35883784, 2022). "MMP-9 has been implicated in the degradation of ECM in both normal physiology and in lung diseases such as BOS36–39." (PMID 35589861, 2022). "Dysregulation of MMP9 is involved in various diseases, such as neurological disorders, inflammatory diseases, cardiovascular diseases, and lung diseases." (PMID 34587931, 2021). "In this regard, it is remarkable that even clinical stable CF patients with mild pulmonary disease revealed an imbalance of the MMP-9/TIMP-1 ratio in BAL indicating the contribution of the proteases in the chronic inflammatory process in CF lung disease." (PMID 26185365, 2015). "Disruption of the balance between MMP-9 and endogenous inhibitors (including TIMP-1, also described as protease/antiprotease imbalance) has been implicated in the pathology of these pulmonary diseases." (PMID 26264019, 2015). "Due to the overlap of alterations in MMP-9 and SP-D in pulmonary diseases and infections, we sought to examine the effects that MMP-9 has upon SP-D in vitro." (PMID 22860023, 2012). "MMP9 has been shown to play important roles in other lung diseases and is critical in neutrophilic inflammation after ventilator-induced lung injury." (PMID 20049209, 2009). "The role of MMP-9 has been studied in several canine pulmonary diseases, and the levels of MMP-9 in bronchial alveolar lavage fluid are increased in recurrent bronchopneumonia, bronchiectasis, eosinophilic bronchopneumopathy, and induced models of airway inflammation." (PMID 38341543, 2024). "Several studies have investigated the link between MMP-9 and CF lung disease severity." (PMID 39011515, 2024). "A higher level of MMP-9 has been reported in influenza A virus-infected murine lung, whereas virus-infected MMP-9 deficient mice showed lower viral titer, being protected from lung disease by an effective immune response." (PMID 37447286, 2023). "Our results show that ITGAM and MMP9 proteins are mainly dysregulated for leukocyte transendothelial migration, indicating that they might promote lung disease related to SSc by affecting this procedure." (PMID 36732374, 2023). "Therefore, we used β-epithelial Na+ channel-overexpressing transgenic (βENaC-Tg) mice as a model of CF-like lung disease and determined the effect of genetic deletion of Mmp9 (Mmp9-/-) on key aspects of the pulmonary phenotype." (PMID 36362203, 2022). "Many studies have reported the involvement of MMP9 in the development of lung diseases." (PMID 36042908, 2022). "Matrix metalloproteinases, especially MMP‐9, are involved in several pulmonary diseases in dogs." (PMID 33274549, 2021). "In other sort of studies researchers tried to find out MMP-9 activity in various lung diseases." (PMID 32944046, 2020). "In addition, MMP-9 has been shown to play important roles in other lung diseases and is critical in neutrophilic inflammation after ventilator-induced lung injury." (PMID 30616599, 2019). "Elevated MMP-9 and MMP-2 activities have been linked to numerous lung disorders." (PMID 30114253, 2018). "MMP-9 has a significant role in this kind of lung disorder and its exacerbation." (PMID 24829780, 2014). "In summary, we have shown that adult and pediatric CF patients with moderate to severe CF lung disease exhibit increased serum levels of MMP-8, MMP-9, and YKL-40 and that this association occurs rather organ specific as is not influenced by the co-existence or absence of CFLD." (PMID 25545245, 2014). "Both gelatinases have been implicated in the pathogenesis of inflammation-related lung diseases; we also reasoned that MMP-2 expression might be enhanced to compensate for MMP-9 deletion." (PMID 18007984, 2007).
lung diseases (continued). "Thus, we hypothesized that a MMP-9/-12 generated fragment of elastin may be a relevant biochemical maker for lung diseases." (PMID 22818364, 2012). "The TNFRSF12A signaling pathway has been identified in IPF to accelerate collagen synthesis through the regulation of matrix metalloproteinase 9 (MMP9), which has been suggested as a therapeutic target in several lung diseases." (PMID 39767799, 2024). "In our study, this pathway was significantly extracted from general SSc (upregulated proteins) and lung disease related to SSc (downregulated proteins) subgroups (ITGB1;ACTN1;ICAM1;ITGAM;MMP9)." (PMID 36732374, 2023). "Currently, MMP-9 and MMP-2 have been reported to be essential factors for the clinical pathology of pulmonary disorders." (PMID 38047016, 2023). "Specifically, we monitored survival, measured MMP-9 and other inflammatory markers in BAL fluid, and assessed airway mucus content and structural lung disease in lung sections of wild-type (WT), Mmp9-/-, βENaC-Tg and βENaC-Tg/Mmp9-/- littermates." (PMID 36362203, 2022). "In the study of the association of MMPs with various diseases such as vascular disease, lung disease, and cancer, MMP-2 and MMP-9 have been extensively studied due to their broad substrate specificity." (PMID 36142454, 2022). "To study the potential contribution of MMP-9 in the pathogenesis of CF-like lung disease, we assessed levels of secreted MMP-9 protein in BAL supernatant of adult WT, Mmp9-/-, βENaC-Tg and βENaC-Tg/Mmp9-/- mice by gelatin zymography." (PMID 36362203, 2022). "Therefore, activation of MMP-2 and MMP-9 may play an important role in pulmonary diseases." (PMID 30616599, 2019). "Adults and children with moderate to severe CF lung disease exhibited significantly increased serum expression of MMP-8, MMP-9, YKL-40 and TIMP-1." (PMID 25545245, 2014). "Our data indicated that in cardiovascular tissue, elastin degradation by MMP-9 and-12 leads to the release of the ELM-2 neoepitope while the degradation in pulmonary diseases leads to the release of the ELM neoepitopes." (PMID 23805173, 2013). "We conclude that MMP-9 does not play a major role in the in vivo pathogenesis of CF-like lung disease in mice." (PMID 36362203, 2022). "Pentadecanoylcarnitine also had dose-dependent tissue remodeling activities in two cell systems relevant to lung disease, fibrosis, and wound healing, including lowered plasminogen activation inhibitor 1 (PAI-1), matrix metallopeptidase 1 and 9 (MMP1, MMP9), and tissue plasminogen activator (tPA)." (PMID 35999445, 2022). "Collectively, our data do not support a major role of MMP-9 in the in vivo pathogenesis of CF-like lung disease in mice." (PMID 36362203, 2022). "The impact of PDE4 inhibitors on MMP expression and/or activity has been previously reported, mostly in the context of pulmonary diseases, in which these drugs abolish the enhanced elastolytic activity driven by inflammatory stimulus and attenuate MMP-2 and/or MMP-9 levels." (PMID 33809405, 2021). "This relationship was specific for MMP-9 activity, as neither human neutrophil elastase nor myeloperoxidase activity predicted subsequent lung disease severity in either the RSV or control groups." (PMID 26264019, 2015). "Liver and pancreas represent two other organ systems that are, apart from the lung, frequently affected by CF and thus might act as potential confounders of the observed up-regulation of MMP-8, MMP-9, YKL-40 and TIMP-1 in CF lung disease." (PMID 25545245, 2014). "The pathogenesis of lung diseases such as COPD and IPF involves an inflammatory response, and tissue turnover is mediated in part by activated macrophages, which secrete their signature panel of proteases, including MMP-9 and -12." (PMID 22818364, 2012). "In this study, we identified significant increases of active MMP-9 in a series of 33 children with ARDS compared to non-pulmonary disease controls at 48 hours of intubation, independent of age, gender, disease etiology and severity." (PMID 21857935, 2011).
lung diseases (continued). "Thus, we can suggest that the downregulation of MMP9, observed in CF PBMCs treated with VX770, could represent one of the possible positive effects of this drug in decreasing lung disease progression." (PMID 33920274, 2021). "Hence, MMP-8, MMP-9, and YKL-40 might represent novel serological markers of CF lung disease and pulmonary exacerbations." (PMID 25545245, 2014). "Our group has previously demonstrated that individuals without known lung disease have very low MMP-9 activity, Ac-PGP levels, and PMN burden suggesting that there may be dysregulation of important protease-mediated inflammatory mechanisms in chronic neutrophil-predominant lung disorders such as CF." (PMID 21249198, 2011). "Together, these data indicate that the observed increased expression of MMP-8, MMP-9, YKL-40, and TIMP-1 occur indeed relatively specific for the existence of CF lung disease without being affected by pancreas and liver disease as other major manifestations of CF." (PMID 25545245, 2014).